GDF2 (growth differentiation factor 2)
Diseases named in the same sentence as GDF2 in open-access papers:
GDF2 is named in the same sentence as 158 diseases in open-access papers, as found by Europe PMC text mining. Sharing a sentence is not in itself a finding about the gene and the disease. The quoted sentences say what the papers report.
pulmonary arterial hypertension (42 papers, 2015 to 2026). "Subsequent 14 gene pulmonary arterial hypertension panel revealed a pathogenic deletion of the entire coding sequence of GDF2 as well as a VUS in bone morphogenetic protein receptor type 1B (BMPR1B)." (PMID 40429357, 2025). "Heterozygous deleterious mutations in the GDF2 gene (which encodes for BMP9) have been reported in patients with pulmonary arterial hypertension and result in reduced circulating concentrations of BMP9." (PMID 33320799, 2021). "Longitudinal follow-up is planned for the proband, with additional genetic testing (e.g., for ENG, MADH4, and GDF2) to be performed if pulmonary hypertension symptoms manifest." (PMID 40933708, 2025). "Deleterious mutations in the GDF2 gene, encoding BMP9, are causative of pulmonary arterial hypertension and hereditary haemorrhagic telangiectasia." (PMID 41222740, 2025). "Patient 2 in our cohort presented with pulmonary arterial hypertension, which prompted genetic testing that identified his GDF2 deletion and secondarily the diagnosis of HHT." (PMID 40429357, 2025). "According to the pulmonary hypertension gene curation expert panel of pulmonary hypertension of ClinGen, the association of BMPR2, KCNK3, KDR, SMAD9, and TBX4 and PH is definitive, GDF2 is strong, and AQP1 has a limited disease relationship." (PMID 35627312, 2022). "Many pulmonary arterial hypertension genetic panels include GDF2." (PMID 40429357, 2025). "Additionally, our cohort had a higher frequency of pulmonary hypertension than cohorts of children with other HHT variants, potentially indicating a unique phenotype for GDF2." (PMID 40429357, 2025). "The significance of the BMP9–ALK-1/BMPR2-mediated signal in endothelial cell is supported by the causal mutations identified in pulmonary arterial hypertension and hereditary hemorrhagic telangiectasia patients in the ACVRL1 and GDF2 genes, which encode ALK-1 and BMP9, respectively." (PMID 30272025, 2018). "Patients with GDF2-related pulmonary hypertension may need to be evaluated for brain and lung AVMs." (PMID 40429357, 2025). "This deletion was classified as pathogenic based on a previous report of two individuals with a full gene deletion of GDF2 with pulmonary arterial hypertension but notably no clinical features of HHT." (PMID 40429357, 2025).
hereditary hemorrhagic telangiectasia (40 papers, 2012 to 2025). A disorder of angiogenesis leading to arteriovenous dilatations: cutaneo-mucosal hemorrhagic telangiectasias and visceral shunting. "Background/Objectives: Pathogenic variants in the growth differentiation factor 2 (GDF2) gene have been linked to a hereditary hemorrhagic telangiectasia (HHT)-like syndrome, yet their clinical significance remains under investigation." (PMID 40429357, 2025). "Ultra‐rare pathogenic GDF2 variants are reported in hereditary hemorrhagic telangiectasia and overlapping disorders characterized by telangiectasias and arteriovenous malformations (AVMs)." (PMID 36259599, 2023). "The endogolin (ENG)g (*131195), activin A receptor type 1 (AVCRL1) (*601284), SMAD4 (SMAD family member 4) (*600993), and growth differentiation factor 2 (GDF2) (*605120) genes have been identified as the underlying cause of hereditary hemorrhagic telangiectasia." (PMID 31594285, 2019).
liver fibrosis (30 papers, 2014 to 2025). "Pdgfb expression was significantly upregulated in KCs and ECs after Gdf2 and Bmp10 deletion, ultimately leading to HSCs activation and liver fibrosis." (PMID 39453386, 2024). "Picrosirius red (PSR) staining revealed increased collagen deposition in the livers of Gdf2/Bmp10HSC-KO mice at the age of 12 weeks, suggesting that these mice presented liver fibrosis." (PMID 39453386, 2024). "In view of liver fibrosis, Gdf2/Bmp10HSC-KO mice may be a better mouse model to mimic the liver pathology observed in HHT patients." (PMID 39453386, 2024). "Moreover, BMP9 (also called growth differentiation factor 2 (GDF2)) is involved in liver fibrosis, heart failure, tumors, glucose metabolism, and lipid metabolism." (PMID 35923297, 2022). "Thus, the correlation between Gdf2/Bmp10 expression and liver fibrosis needs further investigation." (PMID 39453386, 2024). "A key ligand regulating vascular homeostasis, BMP9 (also known as GDF2), is synthesized in the liver and contributes to liver fibrosis in adult sinusoids downstream of LSEC de-differentiation." (PMID 37787089, 2023).
breast carcinoma (22 papers, 2015 to 2025). "Similarly, loss of GDF2/BMP9, in a mouse model of breast cancer, was associated with increased tumor growth and metastasis, indicating a protective role of this gene." (PMID 36611168, 2023).
hepatocellular carcinoma (21 papers, 2012 to 2025). A malignant tumor that arises from hepatocytes. "To investigate the interaction between BMP9 and angiogenic factors in HCC, we first explored the gene expression correlation between BMP9 (GDF2) and the angiogenic proteins VEGFR2 (KDR) and HIF-1α (HIF1A) in The Cancer Genome Atlas Liver Hepatocellular Carcinoma (TCGA-LIHC) cohort." (PMID 35163396, 2022).
ovarian carcinoma (16 papers, 2012 to 2025). A malignant neoplasm originating from the surface ovarian epithelium. "GDF2 suppresses breast and ovarian cancer metastasis, while GDF9 (up-regulated 3.75-fold by curcumin) exhibits tumor-suppressive effects in bladder cancer." (PMID 40430278, 2025). "This same study also observed higher GDF2 promoter methylation in tumors of ovarian cancer patients compared to normal individuals." (PMID 36611168, 2023).
liver cancer (13 papers, 2013 to 2024). An epithelial or non-epithelial malignant neoplasm that arises from the liver. "Compared to the level detected in normal liver cells, the GDF2 expression level was reduced in two common liver cancers, liver hepatocellular carcinoma and cholangiocarcinoma, but not in other cancer types." (PMID 37132170, 2023).
Obesity (13 papers, 2015 to 2025). Accumulation of substantial excess body fat. "In conclusion, a combination of upregulated obesity-related CVRPs (ANGPT1, IL, 1Ra, XCL1) and downregulated cardioprotective proteins (sRAGE, BMP6, Mn-SOD, GDF2) in PCOS may contribute to the increased risk of CVDs in overweight women with PCOS." (PMID 39858399, 2024).
Hypertension (10 papers, 2017 to 2025). The presence of chronic increased pressure in the systemic arterial system. "GDF-2 has been suggested as a biomarker for cardiovascular disease since its levels are lower in individuals with essential hypertension and coronary heart disease compared with controls." (PMID 36180668, 2023). "Based on their disease–gene associations, these biomarkers are involved in vascular inflammation (HO-1, LPL, PAPPA, ADAMTS13, ADM, PGF, and GDF-2), hypertension, and arterial disease (PAPPA, ADAMTS13, ADM, and PGF)." (PMID 35327515, 2022).
juvenile polyposis (9 papers, 2016 to 2026). "MADH4 variants cause juvenile polyposis/HHT overlap syndrome, while GDF2 encodes BMP9, which can bind to endoglin protein and ALK1 protein, leading to overlapping phenotypes of HHT1 and HHT2." (PMID 40933708, 2025). "Mutations in mothers against decapentaplegic homolog 4 (SMAD4), associated with juvenile polyposis, and in growth differentiation factor 2 (GDF2, also known as BMP-9), are much rarer." (PMID 40007589, 2025). "Other genes with mutations contributing to some cases of HHT include MADH4, which encodes SMAD4 (leading to the juvenile polyposis-HHT phenotype), and GDF2, which encodes BMP9, a ligand of ALK1 (HHT5 phenotype)." (PMID 41303195, 2025). "Taken together, HHT1 and HHT2 account for more than 80% of all HHT cases, whereas a small number of patients show mutations in SMAD4 (MADH4) or in BMP9 gene (GDF2), which are responsible for less common HHT variants such as a combined syndrome with juvenile polyposis (JP-HHT) and HHT5, respectively." (PMID 30761306, 2019).
Telangiectasia (8 papers, 2015 to 2025). Telangiectasias refer to small dilated blood vessels located near the surface of the skin or mucous membranes, measuring between 0.5 and 1 millimeter in diameter. "Given that telangiectasias in some people with GDF2 have been reported to have different appearances than in those with other genetic variants, we did not limit reporting of telangiectasias in this pediatric cohort of children with HHT to those with lesions in characteristic areas." (PMID 40429357, 2025). "We suggest that the telangiectasias documented in homozygous GDF2 variant carriers lacking BMP9 in our earlier study may reflect the additional loss of circulating BMP10." (PMID 36259599, 2023). "In a cohort aged 16–21 years with non-GDF2 pathogenic HHT variants, skin telangiectasias were found in only 49%, so it may not be surprising that only three of our seven patients had telangiectasias at diagnosis." (PMID 40429357, 2025). "When our group reported last year that mutations in GDF2 were found in three patients with a telangiectasia syndrome, a decision was made to stop short of labeling it a new type of HHT, because it was not clear that the dermal telangiectases were typical of HHT as described in the Curaçao criteria." (PMID 25674101, 2015).
vascular malformation (4 papers, 2016 to 2024). A non-neoplastic disorder that is the result of defects of vascular morphogenesis. "First, we performed manual analysis and variant calling of the sequencing data for the genes known to cause HHT (ACVRL1, ENG, GDF2, SMAD4) or vascular malformation syndromes with similar phenotypes (EPHB4, RASA1), as well as PIK3CA, which has been shown to modify vascular malformation phenotypes." (PMID 39062925, 2024).
epistaxis (2 papers, 2017 to 2025). Bleeding from the nose. "While this patient’s symptoms of HHT are likely related to her ENG variant, synergy cannot be excluded, and two first-degree family members with clinically significant epistaxis also have the same GDF2 VUS." (PMID 40429357, 2025). "The patient’s HHT symptoms are most likely due to her ENG pathogenic variant, but given her father and half-brother’s clinically significant epistaxis, a synergistic contribution of her GDF2 VUS to her symptoms cannot be excluded completely." (PMID 40429357, 2025). "Also, we chose to include our patient with a GDF2 VUS and a de novo pathogenic ENG variant because of the interesting possibility of synergy and because both her father and paternal half-brother have clinically significant epistaxis and harbor the same GDF2 VUS." (PMID 40429357, 2025).
liver cirrhosis (2 papers, 2023 to 2024). "Given that GDF2 and BMP10 regulated the expression of Gata4 in murine ECs, it is possible that the reduced expression of GATA4 may be due to low expression of GDF2 and BMP10 in liver cirrhosis." (PMID 39453386, 2024).
cerebral aneurysm (1 paper, 2025). "While familial testing for the GDF2 variant has not been completed, it was recommended due to the history of a maternal grandmother with a suspected cerebral vascular malformation and a maternal uncle who died at the age of 28 due to a ruptured cerebral aneurysm." (PMID 40429357, 2025).
glioma (1 paper, 2023). A benign or malignant brain and spinal cord tumor that arises from glial cells (astrocytes, oligodendrocytes, ependymal cells). "GDF2‐ACVRL1 can modulate glioma angiogenesis, but its association with microglia was elusive." (PMID 36681858, 2023).
Pulmonary arteriovenous malformation (1 paper, 2021). Pulmonary arteriovenous malformation, a condition most commonly associated with hereditary hemorrhagic telangiectasia, is an abnormal communication between the pulmonary artery and pulmonary vein without an intervening capillary communication. "We studied two pediatric patients homozygous for GDF2 (BMP9 gene) nonsense mutations: one with PAH (c.[76C>T];[76C>T] or p.[Gln26Ter];[Gln26Ter] and a new individual with pulmonary arteriovenous malformations (PAVMs; c.[835G>T];[835G>T] or p.[Glu279Ter];[Glu279Ter]); both with facial telangiectases." (PMID 33834622, 2021).
pulmonary veno-occlusive disease (1 paper, 2015). "Most recently, further rare mutations in genes linked to the BMP signaling pathway have been identified such as KCNA3 or KCNA5 mutations in IPAH, CAV-1, BMP9/GDF2 in HPAH, EIF2AK4 in patients with pulmonary veno-occlusive disease." (PMID 26167679, 2015).
testicular cancer (1 paper, 2023). A primary or metastatic malignant neoplasm that affects the testis. "Specific to testicular cancer, decreased methylation in sperm was observed within the promoter of GDF2 in our patient cohort, a result also seen in a subset of TC patients 2–3 years post-treatment in the validation cohort." (PMID 36611168, 2023).
tumor (60 papers, 2012 to 2026). "Deletion of Gdf2, the gene encoding BMP9, leads to enhanced tumor growth and increased lung metastases in the syngeneic orthotopic E0771 mouse model of metastatic breast cancer." (PMID 34926282, 2021). "In contrast, despite reducing tumor volume, deficiency for Gdf2 gave rise to an enhanced incidence of micrometastatic lesions in the liver." (PMID 27741515, 2016). "Already in 2015, it was reported that the GDF2 promoter can be silenced by methylation in ovarian cancer patients, resulting possibly in tumor promotion." (PMID 41378712, 2025). "Vessel normalisation‐related genes, including GDF2, were also significantly downregulated in tumour cells isolated from HBV‐infected HCC tissues compared with HBV‐uninfected HCC tissues." (PMID 37132170, 2023). "At the same time, the presence of cell migration inhibitors (APOE, AKT1, BARD1, GDF2) in exosomes from blood HFs accompanied by low stimulating effects on the migration velocity of tumor cells." (PMID 32218180, 2020). "In vivo, we also analyzed tumor necrosis and found that the percentage of necrosis was significantly higher in Gdf2−/− mice than WT mice." (PMID 30165893, 2018). "It is also possible that, as for the primary tumor, the growth of the metastases would be favored in Gdf2−/− mice." (PMID 30165893, 2018). "Gdf2 deletion increased tumor growth while inhibiting vessel maturation and tumor perfusion." (PMID 30165893, 2018). "Furthermore, the knockout of Gdf2 (BMP9), the primary ligand for ALK1 and endoglin, exhibited a mixed phenotype from each of ALK1 and endoglin deficiencies; overall primary tumor burden decreased, but hepatic metastases increased." (PMID 27741515, 2016). "Furthermore, we have utilized mice deficient for BMP9 (gene name Gdf2) to investigate the impact of ligand binding to ALK1 and endoglin on tumor parameters." (PMID 27741515, 2016). "Notably, bone morphogenetic protein 9 (BMP9), which is encoded by the growth differentiation factor 2 (GDF2) gene, is an important mediator of pericyte recruitment and may also be a promising target for the normalisation of tumour vasculature." (PMID 37132170, 2023). "As we could not observe any effect of BMP9 on tumor cell proliferation that could explain the increase in tumor size in Gdf2−/− mice, we next addressed whether the loss of BMP9 could be due to an effect on tumor angiogenesis." (PMID 30165893, 2018). "The tumor volume and number for RIP1-TAg2; Gdf2+\− mice were intermediate between the wildtype and knockout phenotypes, demonstrating a gene dosage effect." (PMID 27741515, 2016). "This was not due to tamoxifen injection as Gdf2-KO mice injected with tamoxifen also showed significantly increased tumor growth (data not shown)." (PMID 30165893, 2018). "We found that the percentage of tumor vessels perfused by lectin was significantly reduced in Gdf2 −/− versus WT mice, supporting a defect in vessel perfusion in absence of BMP9." (PMID 30165893, 2018). "In addition, GDF2 was not signally expressed in normal and tumor gastric tissues." (PMID 40153751, 2025).
cancer (33 papers, 2012 to 2025). A tumor composed of atypical neoplastic, often pleomorphic cells that invade other tissues. "E0771 cancer cells were orthotopically injected into the fourth mammary gland of 6-week-old WT and Gdf2-deficient mice in the C57BL/6 background." (PMID 30165893, 2018). "This locus encodes the GDF2 protein, also known as bone morphogenic protein 9 (BMP9), a member of the TGFβ superfamily, which has roles in cancer progression." (PMID 36611168, 2023). "BMP9 (also known as growth differentiation factor 2)is a member of BMPs and has different functions in distinct cancers." (PMID 28415788, 2017). "Similarly, of the genes associated with CIN3/cancer, C1RL, GDF10, and GDF2 were also associated with persistence (p-values of 0.00875, 0.0423, and 0.04080, respectively)." (PMID 22496757, 2012). "From the cancer studies, the increased methylation of SPON2 in the sperm of HD patients would result in decreased expression, while the decreased methylation of GDF2 in the sperm of the TC patients would result in increased expression." (PMID 36611168, 2023). "GDF2 (also known as BMP-9), a member of the transforming growth factor β superfamily, promotes the proliferation and migration of cancer cells." (PMID 34212052, 2021). "The role of BMP9, using a similar approach of Gdf2 knockdown, has recently been described in the pancreatic RIP1-TAg2 PanNETS cancer model." (PMID 30165893, 2018).
vascular disorder (4 papers, 2012 to 2023). A general term used to describe any disease affecting blood vessels]. "In this study, we tested for mutations in two genes, RASA1 and GDF2, which were recently reported to be involved in vascular disorders." (PMID 27081547, 2015).
GDF2 also shares sentences with these, for which no sentence is quoted: infection (18 papers); pulmonary hypertension (18); liver disease (14); cardiovascular disease (11); Cirrhosis (9); Hepatic steatosis (8); Insulin resistance (8); myeloma (8); osteosarcoma (8); portopulmonary hypertension (7); prostate carcinoma (7); arteriovenous malformations (6); atherosclerosis (6); endothelial dysfunction (6); heart failure (6); metabolic syndrome (6); nonalcoholic fatty liver disease (6); osteoporosis (6); bladder cancer (5); diabetes (5); fibrosis (5); Alzheimer disease (4); coronary heart disease (4); liver (4); pancreatic cancer (4); Sepsis (4); amyloid (3); anemia (3); breast tumor (3); colon cancer (3).
A further 106 diseases each share a sentence with GDF2 in 3 papers or fewer.